IQCB1 (IQ motif containing B1)
Description:
Involved in ciliogenesis. The function in an early step in cilia formation depends on its association with CEP290/NPHP6. Involved in regulation of the BBSome complex integrity, specifically for presence of BBS2 and BBS5 in the complex, and in ciliary targeting of selected BBSome cargos. May play a role in controlling entry of the BBSome complex to cilia possibly implicating CEP290/NPHP6.
Synonyms: PIQ; KIAA0036; NPHP5; SLSN5
Tractability: PROTAC: ubiquitination databases record sites on it; its protein half-life has been measured.
Gene: Protein-coding gene on chromosome 3 (121,769,399 to 121,835,093, reverse strand). Ensembl gene ENSG00000173226.
Subcellular location: Cytoplasm, cytoskeleton, microtubule organizing center, centrosome; Cytoplasm, cytoskeleton, microtubule organizing center, centrosome, centriole
Subcellular location (Human Protein Atlas): Cytokinetic bridge; Microtubules; Mitotic spindle; Basal body; Nucleoplasm; Primary cilium
Pathways (Reactome):
Organelle biogenesis and maintenance: Anchoring of the basal body to the plasma membrane
Gene Ontology:
Molecular function: BBSome binding; calmodulin binding; enzyme binding; protein binding; protein-macromolecule adaptor activity
Biological process: cilium assembly; cytosolic ciliogenesis; maintenance of animal organ identity; photoreceptor cell maintenance; protein localization to ciliary transition zone
Cellular component: centrosome; ciliary basal body; extracellular exosome; photoreceptor connecting cilium; ciliary transition zone; cilium; cytosol; centriole; photoreceptor outer segment
Genetic constraint (gnomAD): Loss-of-function variants: 35 observed, 52.19 expected, observed/expected ratio (o/e) 0.67, 90% interval 0.51 to 0.89. The upper end of that interval is the gene's LOEUF score, 0.89, which puts it in group 3 of 6, group 1 being the genes least tolerant of losing a copy. Missense variants: 382 observed, 432.81 expected, observed/expected ratio (o/e) 0.88, 90% interval 0.81 to 0.96. Synonymous variants: 126 observed, 154.93 expected, observed/expected ratio (o/e) 0.81, 90% interval 0.7 to 0.94.
Gene-disease validity (ClinGen):
ClinGen rates the evidence that IQCB1 causes each of these diseases.
ciliopathy (autosomal recessive): Definitive. A genetic disorder of the cellular cilia or the cilia anchoring structures, the basal bodies, or of ciliary function.
Homologues: Orthologues: chimpanzee IQCB1 (99% identical), macaque IQCB1 (97% identical), dog IQCB1 (89% identical), pig IQCB1 (88% identical), rat Iqcb1 (87% identical), mouse Iqcb1 (87% identical), rabbit IQCB1 (86% identical), guinea pig IQCB1 (83% identical), tropical clawed frog iqcb1 (48% identical), zebrafish iqcb1 (37% identical), zebrafish iqcb1 (25% identical).
Diseases named in the same sentence as IQCB1 in open-access papers:
IQCB1 is named in the same sentence as 38 diseases in open-access papers, as found by Europe PMC text mining. Sharing a sentence is not in itself a finding about the gene and the disease. The quoted sentences say what the papers report.
ciliopathy (16 papers, 2009 to 2025). "To examine ciliopathy phenotypes associated with mutations in the IQCB1 gene causing NPHP5-LCA, we recruited 4 affected patients as well as 3 healthy familial controls from 3 families." (PMID 36084637, 2022). "SLS is a genetically heterogeneous renal–retinal ciliopathy associated with multiple ciliopathy-related genes, including NPHP1, NPHP4, IQCB1, and SDCCAG8." (PMID 40725491, 2025). "Many ciliopathy genes, such as CEP290, IFT140, and IQCB1 initially reported to cause syndromic retinal degeneration, but were later identified as having vital roles in LCA pathogenesis as well." (PMID 33957996, 2021). "Biallelic mutations in the ciliopathy-associated genes AHI1, BBS10, IQCB1, and OFD1 were identified in single patients." (PMID 29974258, 2018). "Ciliogenesis is controlled in part by nephrocystin-5 (NPHP5/IQCB1), and NPHP5 dysfunction causes ciliopathies in humans, mice and dogs." (PMID 28498859, 2017). "Mutations in NPHP5/IQCB1, encoding an IQ-domain protein which localises to the photoreceptor CC, cause the ciliopathy SLS." (PMID 26093275, 2015). "The genes responsible for SLSN are NPHP1, NPHP4, NPHP5/IQCB1 and CEP290, which are the same genes mutated in other ciliopathies such as NPHP and JBTS." (PMID 19439065, 2009). "Similarly, we find multiple genes involved in ciliopathies to be accelerated, including ‘deleted in primary ciliary dyskinesia’ (Dpcd), Iqcb1 (a component of primary cilia), and ciliary neurotrophic factor (Cntf)." (PMID 29035697, 2017).
Senior-Loken syndrome (13 papers, 2011 to 2025). Senior-Loken syndrome (SLSN) is a very rare autosomal recessive oculo-renal disease characterized by the association of nephronophthisis (NPHP), a chronic kidney disease, with retinal dystrophy. "On the other hand, mutations in the IQCB1 gene at the NPHP5 locus have been shown to cause a form of Senior-Loken syndrome characterized by a congenital retinal dystrophy associated with a renal dysfunction of highly variable age of onset (1st to 5th decade)." (PMID 23308101, 2013). "In our cohort of 17 Korean patients with genetically confirmed Senior-Loken syndrome (SLS), four causative genes were identified: NPHP1 (35.3%), NPHP4 (29.4%), IQCB1 (29.4%), and SDCCAG8 (5.9%)." (PMID 40725491, 2025). "NPHP5/IQCB1 is a causal gene of LCA and Senior-Löken syndrome (SLS), and LCA and SLS patients with NPHP5 mutations phenocopy CEP290-LCA and CEP290-SLS cases." (PMID 34520396, 2021). "CIC00953 was found to be compound heterozygous for two small deletions in IQCB1 including one already reported in Senior-Loken syndrome and one novel." (PMID 26103963, 2015). "Mutations in the IQ calmodulin-binding motif containing B1 (IQCB1)/NPHP5 gene encoding the ciliary protein nephrocystin 5 cause early-onset blinding disease Leber congenital amaurosis (LCA), together with kidney dysfunction in Senior-Løken syndrome." (PMID 36084637, 2022). "The IQCB1 gene (IQ calmodulin-binding motif-containing protein-1; also known as NPHP5) is located on chromosome 3q13.33, with pathologic variants associated with Senior-Loken syndrome (SLS), a rare autosomal recessive condition involving renal dysfunction and LCA/EOSRD." (PMID 38522724, 2024).
nephronophthisis (11 papers, 2011 to 2025). Progressive tubulointerstitial injury, inherited in an autosomal recessive pattern, caused by mutations in genes involved in ciliary function, which may result in an end stage renal failure. "For example, the nephronophthisis linked to IQCB1 mutations could be clinically unmasked belatedly." (PMID 29053603, 2017). "In patients with syndromic nephronophthisis caused by several genes (including NPHP3, IQCB1, CEP290, and MKS1), an additional heterozygous variant in RPGRIP1L is associated with retinitis pigmentosa." (PMID 37628633, 2023). "Common variants are associated with elevated creatine in association studies;In patients with syndromic nephronophthisis caused by several genes (including NPHP3, IQCB1, CEP290, and MKS1), an additional heterozygous variant in RPGRIP1L is associated with retinitis pigmentosa." (PMID 37628633, 2023). "Homozygous and compound heterozygous variants in the IQCB1 gene have been associated with LCA with or without the renal phenotype of nephronophthisis." (PMID 35409265, 2022). "In this case, sequencing and MLPA analysis of NPHP1 was also performed, together with the sequence analysis of other rarer genes related to nephronophthisis (INVS, NPHP3, NPHP4, IQCB1): no pathogenic variant was found in these genes." (PMID 37372410, 2023).
Leber congenital amaurosis (8 papers, 2010 to 2025). Leber congenital amaurosis (LCA) is a retinal dystrophy defined by blindness and responses to electrophysiological stimulation (Ganzfeld electroretinogram (ERG)) below threshold, associated with severe visual impairment within the first year of life. "Patients with IQCB1 mutations were generally prone to early and severe retinal degeneration, typically manifesting as Leber congenital amaurosis (LCA) (three patients), while two patients exhibited milder RP sine pigmento with preserved central vision." (PMID 40725491, 2025). "Patients with IQCB1 (NPHP5) mutations (n = 5, 29.4%) typically displayed early and severe retinal degeneration, characterized by congenital blindness due to Leber congenital amaurosis (LCA) in three cases." (PMID 40725491, 2025). "We now show that this shorter PRL transcript is also expressed in RPGR-XLPRA1 (X-Linked Progressive Retinal Atrophy 1, caused by a five-nucleotide deletion in the RPGR exon ORF15) and NPHP5-LCA (Leber Congenital Amaurosis, caused by a single nucleotide insertion in exon 10 of the IQCB1/NPHP5 gene)." (PMID 39294136, 2024). "Mutations in the gene encoding IQ calmodulin-binding motif containing B1 (IQCB1/NPHP5) are the most common cause of renal-retinal Senior-Løken syndrome (SLSN) and are also detected in patients with non-syndromic Leber congenital amaurosis (LCA)." (PMID 36084637, 2022). "For example, RPGR exists in complex with NPHP5 (or IQ domain containing calmodulin binding protein [IQCB1]; SLSN), centrosomal protein of 290 kDa (CEP290)/NPHP6 (Leber congenital amaurosis, SLSN, JBTS), and NPHP8/RPGRIP1-like (RPGRIP1L; mutated in JBTS and Meckel-Gruber syndrome) in the retina." (PMID 20664800, 2010). "Machine learning techniques have recently been used to predict treatment potential in two forms of Leber congenital amaurosis (LCA) caused by mutations in CEP290 or IQCB1 (NPHP5), that had little or no measurable vision but some measurable central retinal structure." (PMID 32848570, 2020).
retinal degeneration (7 papers, 2009 to 2025). Degeneration of the retina. "IQCB1 mutations were associated with early-onset retinal degeneration, including LCA, though some patients had preserved renal function." (PMID 40725491, 2025). "One of the fifty high impact variants resided in a gene known to cause retinal degeneration (IQCB1) and listed on RetNet." (PMID 28322220, 2017). "In contrast, IQCB1-related cases exhibited early-onset retinal degeneration, frequently manifesting as LCA, but some retained normal renal function at diagnosis." (PMID 40725491, 2025). "In contrast to the previous NPHP genes, mutations in the IQCB1 gene, now referred to as NPHP5, were reported only in patients with NPH in combination with severe retinal degeneration and early blindness—SLS." (PMID 18607645, 2009).
retinitis pigmentosa (6 papers, 2011 to 2025). Retinitis pigmentosa (RP) is an inherited retinal dystrophy leading to progressive loss of the photoreceptors and retinal pigment epithelium and resulting in blindness usually after several decades. "Mutations in NPHP5/IQCB1 cause a retinal–renal phenotype characterized by retinitis pigmentosa with NPHP." (PMID 34830133, 2021). "Patients with IQCB1 mutations are characterized by the presence of retinitis pigmentosa with NPHP (renal–retinal or Senior–Løken syndrome)." (PMID 29379777, 2017). "Interestingly, mutations of the IQ motif–containing protein IQCB1 (also known as Nephrocystin-5) cause renal failure and retinitis pigmentosa in humans as a result of ciliary dysfunction." (PMID 24362311, 2014). "In patients with a variety of syndromic ciliopathies attributed to variants in NPHP3, IQCB1, CEP290, and MKS1, a common RPGRIP1L variant (p.Arg229Thr) (present in over 8% of South Asians and 3% of other populations) is significantly enriched in patients who also have retinitis pigmentosa." (PMID 37628633, 2023).
retinal ciliopathy (5 papers, 2019 to 2025). "Finally, variants in the gene encoding NPHP5/IQCB1 also associated with LCA were recently shown to provoke elongated primary cilia in patient-derived fibroblasts and iPSC-derived RPE, further validating that elongated ciliary defects give rise to retinal ciliopathies." (PMID 37768732, 2023).
renal failure (3 papers, 2014 to 2023). "IQCB1 mutation positive LCA patients may be at risk of developing renal abnormalities, however the onset of the renal failure is highly variable and need to be counseled and managed appropriately." (PMID 26147992, 2015).
retinal diseases (3 papers, 2007 to 2025). "In support of this, a recent Korean national study demonstrated the utility of WGS in inherited retinal diseases by identifying large deletions in IQCB1 and PRPF31 that were missed by WES or panel testing." (PMID 40725491, 2025).
Retinal dystrophy (3 papers, 2020 to 2025). Retinal dystrophy is an abnormality of the retina associated with a hereditary process. "In the current cohort of 19 patients, we describe 17 pathogenic IQCB1 variants in patients with retinal dystrophy, with or without renal disease." (PMID 38522724, 2024).
Blindness (2 papers, 2009 to 2017). Blindness is the condition of lacking visual perception defined as a profound reduction in visual perception. "Of 50 genes with high impact variants, only three genes (RASGRF1, IQCB1 and CCDC114) had been previously associated with blindness." (PMID 28322220, 2017).
cone-rod dystrophy (2 papers, 2017 to 2024). Inherited retinal dystrophies that belong to the group of pigmentary retinopathies. "This study suggests that the IQCB1 gene should be screened in all patients with LCA/EOSRD or a severe cone-rod dystrophy, and all patients with identified variants should have renal evaluation." (PMID 38522724, 2024). "IQCB1-retinopathy is a severe early-onset cone-rod dystrophy." (PMID 38522724, 2024).
cervical cancer (1 paper, 2025). A primary or metastatic malignant neoplasm involving the cervix. "Genes such as Wiskott-Aldrich Syndrome Protein (WASP), IQ Motif Containing B1 (IQCB1), Myosin IF (MYOIF) and PDZ Domain Containing 1 (PDZD1) that favour cervical cancer prognosis were found to be expressed in HPV 16 positive macrophages." (PMID 40589751, 2025).
colon cancer (1 paper, 2025). "The rs2681416 variant was also associated with poorer survival in colon cancer patients, and it influenced the expression of the IQCB1 gene, which modulates immune cell infiltration (Th17 cells) in the tumor microenvironment." (PMID 41244914, 2025).
polycystic kidney (1 paper, 2017). "In patient 21, bearing IQCB1 mutations, a subsequent clinical evaluation led to a diagnosis of polycystic kidney." (PMID 29053603, 2017).
Retinal atrophy (1 paper, 2017). A nonspecific term denoting wasting, especially as a result of degeneration, of the retinal pigment epithelium (RPE) and neurosensory retinal cells. "The RASGFR1 and CCDC114 variants were associated with several complex clinical features including retinal atrophy, whereas the phenotype associated with the IQCB1 variant was always PRA with extrarenal manifestations in 10–15% of cases." (PMID 28322220, 2017).
retinopathies (2 papers, 2021 to 2024). "Although not a specific or diagnostic finding, it is noted that the severe loss of cone function (undetectable LA ERGs) in the adult patients with only moderate rod involvement is somewhat unusual for a CORD, and may suggest IQCB1-retinopathy as a differential." (PMID 38522724, 2024).
IQCB1 also shares sentences with these, for which no sentence is quoted: Senior-Løken syndrome (4 papers); Bardet-Biedl syndrome (3); Joubert syndrome (3); Hepatic fibrosis (2); Meckel-Gruber syndrome (2); Usher syndrome (2); allergic disease (1); asthma (1); cerebellar ataxia (1); congenital blindness (1); cyst (1); fibrosis (1); hearing loss (1); macular degeneration (1); nephrolithiasis (1); primary ciliary dyskinesia (1); Primary microcephaly (1); pyelonephritis (1); renal disease (1); thrombotic microangiopathy (1); tumor (1).